NR1H4 (nuclear receptor subfamily 1 group H member 4)
Diseases named in the same sentence as NR1H4 in open-access papers (continued):
Sharing a sentence is not in itself a finding about the gene and the disease.
liver diseases (124 papers, 2012 to 2026). "Among others, the nuclear receptor farnesoid X receptor (FXR), encoded by the NR1H4 gene, has been extensively studied with respect to onset, progression of and recovery from liver disease and hepatic injury." (PMID 36430444, 2022). "A loss of function associated with a mutation in human NR1H4 leads to progressive liver disease and high cholesterol levels, suggesting that FXR may contribute to liver disease." (PMID 36776885, 2023). "In contrast, NRs with established functions linked to lipid metabolic processes and liver disease, most notably Ppara, Nr1h4 (FXRα), Thrb and Rora, were expressed at high levels in both hepatocytes and various NPCs, including hepatic stellate cells, endothelial cells and immune cells." (PMID 36711947, 2023). "NR1H4 variants associated with PFIC (FXR-deficiency, also named PFIC subtype 5) were characterized by a secondary BSEP deficiency, coagulopathy and a rapid progression toward end-stage liver disease." (PMID 41033550, 2025). "To date, no studies have uncovered genetic mutations in NR1H4 genes of hepatic disease among pregnant patients from a relatively large nationally representative sample (n = 197) in China and 1029 local healthy pregnant women." (PMID 35436901, 2022).
atherosclerosis (98 papers, 2010 to 2026). A disease characterized by the build-up of fatty material and calcium deposition in the arterial wall resulting in partial or complete occlusion of the arterial lumen. "Furthermore, an in silico predicted transcription factor NR1H4 is known to impact the expression of cytokine genes underlying inflammatory mechanisms of atherosclerosis." (PMID 35203469, 2022).
dyslipidemia (96 papers, 2007 to 2026). "Hyperlipidemia and other forms of dyslipidemia have been associated with COVID-19 severity and may be related to FXR and NR1H4 BP enrichment." (PMID 34566994, 2021). "It ameliorated dyslipidemia, improved insulin sensitivity, and reversed the expression of UCP2, Nr1H4, and Fiaf." (PMID 38469405, 2024). "Ginsenoside Rb1 (Rb1) oral supplementation ameliorated dyslipidemia, improved insulin sensitivity in HFD-induced obese mice, and reversed the expression of uncoupling protein 2 (UCP2), Nuclear receptor subfamily one group H member 4 (Nr1h4), and Fiaf." (PMID 38469405, 2024).
primary biliary cholangitis (96 papers, 2012 to 2026). Primary biliary cholangitis (PBC) is a chronic and slowly progressive cholestatic liver disease of autoimmune etiology characterized by injury of the intrahepatic bile ducts that may eventually lead to liver failure. "FXRα; NR1H4 represents a valid target for mitigating primary biliary cirrhosis (PBC), NASH, diabetes, and atherosclerosis." (PMID 37893218, 2023).
colitis (87 papers, 2011 to 2026). Inflammation of the colon. "Colon inflammation in rodent models of colitis and in Crohn’s disease patients, is associated with a reduced expression of NR1H4 mRNA87." (PMID 32732949, 2020).
non-alcoholic steatohepatitis (85 papers, 2012 to 2026). "The nuclear receptor, Farnesoid X Receptor (FXR/NR1H4), is increasingly recognized as a promising drug target for metabolic diseases, including nonalcoholic steatohepatitis (NASH)." (PMID 38045226, 2024).
hepatocellular carcinoma (82 papers, 2010 to 2025). A malignant tumor that arises from hepatocytes. "Experimental studies on the NR1H4 gene have shown that high bile acids concentrations cause excessive production of inflammatory cytokines, resistance to apoptosis, and increased cell regeneration, all risk conditions for developing hepatocellular carcinoma (HCC) and cholangiocarcinoma (CCA)." (PMID 35884482, 2022). "In addition, NR1H4 dysfunctions may occur during the progression associated with inflammatory bowel disease, colorectal cancer in the gut, fibrosis and hepatocellular carcinoma in the liver." (PMID 35436901, 2022). "The NRs in the cancer group include RARA (acute promyelocytic leukemia), NR1H4 (hepatocellular carcinoma), ESR1 (breast cancer), and AR (prostate cancer)." (PMID 29065888, 2017). "Furthermore, in vitro experiments in primary mouse hepatocytes and human hepatoma cell lines HuH7 and HepG2 together with in vivo experiments demonstrated that IL-1β exposure was sufficient to suppress transcription of Nr1h4, Abcb11, Abcc2, and Abcg5/8, findings that characterize the PNAC liver." (PMID 29643332, 2018). "In hepatocellular carcinoma, the nuclear translocation of transketolase promotes HDAC3 binding to the NR1H4 promoter, thereby inhibiting FXR expression." (PMID 40656893, 2025). "Recently, NR1H4 has been reported in multiple cancers, including colorectal cancer (CRC), hepatocellular carcinoma (HCC), non-small cell lung cancer (NSCLC), breast cancer, cholangiocarcinoma, cervical cancer." (PMID 36123627, 2022).
non-alcoholic fatty liver disease (82 papers, 2011 to 2026). "There are few reports where activation of Nr1h4 has been shown to alleviate ER stress and hence provide protection in various pathological conditions such as diabetic tubulopathy and non-alcoholic fatty liver disease, and in liver injury caused by ER stress." (PMID 38609183, 2024).
colon carcinoma (58 papers, 2012 to 2025). "Data from the Cancer Genome Atlas revealed that ~12% of colon cancers have hypermethylated nuclear receptor subfamily 1, group H, member 4 (NR1H4) gene, which encodes for FXR." (PMID 29259973, 2017). "MYC is an important mediator of NR1H4 KO-induced signaling pathway changes, and inhibition of NR1H4 activity in colon cancer cells can be used as a choice for targeted therapy." (PMID 37020597, 2023). "In contrast, a recent study manifested that knocking out NR1H4 inhibited colon cancer cell proliferation and promoted apoptosis." (PMID 33397428, 2021). "Previous studies have shown that NR1H4 plays an important role in the development of colon cancer by regulating the stability of c-Myc." (PMID 33042807, 2020). "Again, this is the first report of a clear link of PCSK9 up-regulation in colon cancer, while NR1H4 down-regulation has been reported to result from promoter methylation with this cancer." (PMID 28962550, 2017). "Indeed, 6 out of 10 leading TFs have direct evidence and some experimental validation of their involvement in colon cancer risk and progression: ZNF334, FOXD2, FOXD3, POU3F3, NR1H4, and VSX2." (PMID 41114645, 2025). "Nuclear receptor subfamily 1 group H member 4 (NR1H4) plays an important role in the proliferation and survival of colon cancer." (PMID 37020597, 2023). "It was found that expression of NR1H4 is frequently downregulated by DNA methylation and Kirsten rat sarcoma (KRAS) signaling in colon cancer, which implies a negative relationship between NR1H4 and tumor growth." (PMID 34680577, 2021).
Cholestatic liver disease (46 papers, 2012 to 2026). "Overall, liver-specific Nr1h4 deficiency induced significant liver damage in mice with human-like bile acids, unlike in WT mice, validating its use as a new animal model for cholestatic liver disease." (PMID 40499905, 2025).
liver cancer (45 papers, 2015 to 2026). An epithelial or non-epithelial malignant neoplasm that arises from the liver. "Analysis based on TCGA database indicated that NR1H4 and SOCS2 were downregulated in liver cancer, this suggest NR1H4 and SOCS2 may play an important role in tumorigenesis." (PMID 30787420, 2019). "In addition, a Kaplan–Meier (KM) survival analysis was conducted on the core genes in liver cancer, renal clear cell carcinoma, and glioma, and it was found that TNF, IL6, IFNG, and NR1H4 in liver cancer and TNF and IL1B in renal clear cell carcinoma were associated with survival prognosis." (PMID 40238193, 2025). "So NR1H4 might play critical role in ZINC24469384 induced selectivity against liver cancer." (PMID 30787420, 2019). "More importantly, NR1H4 and NR0B2 transcript expression was reduced in liver cancer patients, underscoring the clinical relevance of this DKO mouse model." (PMID 41460563, 2025). "We previously showed that the combined deletion of nuclear receptors, Farnesoid X Receptor (FXR, NR1H4), and Small Heterodimer Partner (SHP, NR0B2) resulted in spontaneous liver cancer in the year-old male mice." (PMID 41460563, 2025). "Although 15-month-old individual Nr1h4 knockout and individual Nr0b2 knockout mice were previously shown to develop liver cancer, unlike the DKO mice, their incidence does not show 100% penetrance nor sex differences." (PMID 41460563, 2025). "Here, we report that mice lacking bile acid (BA) regulators, Farnesoid X Receptor (FXR also termed NR1H4) and Small Heterodimer Partner (SHP also termed NR0B2), recapitulate the sex difference in liver cancer risk." (PMID 41460563, 2025). "Although DKO female mice do not develop liver cancer, it is pertinent to note that they lack Nr1h4 and Nr0b2 gene expression, display chronic cholestasis similar to their male counterparts, and hence the global gene changes associate with poor OS." (PMID 41460563, 2025). "All together, these results shown that downregulation of NR1H4 and SOCS2 might partly play a key role in promote liver cancer and they maybe used as potential new biomarkers for liver cancer diagnosis." (PMID 30787420, 2019). "In this study, we report that, unlike the males, female Nr1h4-/-, Nr0b2-/- (Fxr-/-, Shp-/-) double knockout (DKO) mice exhibit protection against tumorigenesis and thus mimic the sexual dimorphism in liver cancer incidence observed in clinics." (PMID 41460563, 2025).
colorectal cancer (43 papers, 2011 to 2025). A primary or metastatic malignant neoplasm that affects the colon or rectum. "NR1H4, a bile acid‐activated nuclear receptor, induces the expression of N‐acetylglutamate synthase to regulate glutamine and glutamate metabolism in liver, has been implicated in the development of colorectal cancer." (PMID 37387559, 2023). "In colorectal cancer, NR1H4 activation suppresses the JAK2/STAT3 signaling pathway via trans-activation of the suppressor of cytokine signaling 3 (SOCS3) gene and antagonizes Wnt/β-Catenin signaling, acting as a tumor suppressor." (PMID 40656893, 2025). "Additionally, NR1H4 enhances drug-induced cell death in colorectal cancer by modulating myelocytomatosis oncogene (MYC) expression and Myc protein stability." (PMID 40656893, 2025).
breast carcinoma (37 papers, 2008 to 2025). "It was shown that the activation of FXR (encoded by the NR1H4 gene) inhibited the estrogen signaling pathway in breast cancer and testis tumors." (PMID 33153202, 2020). "As bile-acids are a risk factor for post-menopausal breast-cancer, their high concentrations in breast-cysts/plasma of mammary-tumor patients suggest a role for NR1H4 in disease induction/progression." (PMID 26894976, 2016). "In breast-cancer, NR1H4-protein levels are associated with ER-status and luminal markers." (PMID 26894976, 2016). "In spite of the evidence indicating that NR1H4 is oncogenic, particularly in ER+/breast-cancer, there is also evidence supporting the idea that NR1H4-activation is anti-oncogenic." (PMID 26894976, 2016). "NR1H4-dependent proliferation of ER+/breast-cancer cells is stimulated by estrogen deprivation, which recapitulates menopause and aromatase-inhibitor treatment." (PMID 26894976, 2016). "On the basis of these data, it is currently difficult to establish whether NR1H4 is endowed with oncogenic or onco-suppressive properties in breast cancer and whether targeted therapeutic strategies should be aimed at inhibiting or activating the receptor." (PMID 26894976, 2016).
gallstones (34 papers, 2009 to 2025). Solid crystalline precipitates in the biliary tract, usually formed in the gallbladder, resulting in the condition of cholelithiasis. "Therefore, we speculated that these ICP cases with NR1H4 variants have a high risk for gallstones." (PMID 35436901, 2022). "One allele of NR1H4 R436H, described here, does not associate with markers of liver function or gallstones in the Icelandic population suggesting that this variant might alter rather than completely abolish FXR function." (PMID 30271901, 2018).
intrahepatic cholestasis (29 papers, 2011 to 2026). A cholestasis characterized by impairment of the bile flow caused by obstruction located in the liver. "We identified 5 unique NR1H4 variants from 3 unrelated Chinese patients with low GGT intrahepatic cholestasis from our cohort." (PMID 38641832, 2024). "In line with this, loss-of-function variants in the FXR-encoding gene NR1H4 also cause intrahepatic cholestasis associated with the loss of ABCB11 expression." (PMID 33557414, 2021). "In addition to the mutations in MDR3 and BSEP genes, rare mutations within the FIC1 gene (ATP8B1) present within the bile duct membrane and the FXR gene (NR1H4) were also detected in Caucasian patients diagnosed with intrahepatic cholestasis of pregnancy." (PMID 32384779, 2020).
Sepsis (21 papers, 2017 to 2025). Sepsis is defined as life-threatening organ dysfunction caused by a dysregulated host response to infection. "FXR (NR1H4) is a metabolic NR that regulates bile acid, lipid, and glucose metabolism and has recently been linked to sepsis." (PMID 30897154, 2019).
depression (19 papers, 2015 to 2025). "In the PPI network, DPP4, CYP3A4, EP300 MGAM and NR1H4 showed higher degrees and were identified as essential genes of intestinal microbiota influencing the occurrence of depression through the brain–gut axis." (PMID 37433869, 2023). "In conclusion, the intestinal microbiota can affect the development of depression through the metabolites equol, genistein and quercetin, which act on the critical targets of DPP4, CYP3A4, EP300, MGAM and NR1H4." (PMID 37433869, 2023). "We found that intestinal microbiota metabolites such as quercetin, equol, and glycocholic acid can affect the course of depression by acting on targets such as MGAM and NR1H4." (PMID 37433869, 2023).
cholangiocarcinoma (15 papers, 2011 to 2025). A carcinoma that arises from the intrahepatic biliary tree (intrahepatic cholangiocarcinoma) or from the junction, or adjacent to the junction, of the right and left hepatic ducts (hilar cholangiocarcinoma). "We also data mining using public TCGA data sets to examine the expression of NR1H4 and SOCS2 in Liver Hepatocellular Carcinoma (LIHC) and Cholangiocarcinoma." (PMID 30787420, 2019).
diabetic nephropathy (13 papers, 2014 to 2025). "Conversely, Nr1h4 (the gene encoding FXR) deletion worsens renal injury in STZ-induced diabetic mice, suggesting FXR as a promising therapeutic target in diabetic nephropathy." (PMID 41438090, 2025).
prostate carcinoma (13 papers, 2014 to 2024). A carcinoma that arises from epithelial cells of the prostate gland. "Many of the immune response related (e.g., IRF8, JAK3, PTGER4, RELB, IFITM3) and part of the lipid metabolism related genes (e.g., NR1H4, PPARGC1B, PLIN1, HSD17B14) were identified to be adaptive which addressed their significance for prostate cancer." (PMID 36809527, 2023).
familial intrahepatic cholestasis (10 papers, 2016 to 2025). An instance of intrahepatic cholestasis that is caused by an inherited modification of the individual's genome. "NR1H4 mutations in humans cause a severe liver injury called progressive familial intrahepatic cholestasis." (PMID 40499905, 2025). "Furthermore, previous studies have demonstrated that functional variants in NR1H4 are associated with ICP disease/progressive familial intrahepatic cholestasis." (PMID 35436901, 2022). "Genes associated with familial intrahepatic cholestasis (FIC) include ATP8B1 (FIC1), ABCB11 (FIC2), ABCB4 (FIC3), TJP2 (FIC4), NR1H4 (FIC5) and MYO5B (FIC6)." (PMID 33557414, 2021).
progressive familial intrahepatic cholestasis (8 papers, 2018 to 2025). Progressive familial intrahepatic cholestasis (PFIC) refers to a heterogeneous group of autosomal recessive disorders of childhood that disrupt bile formation and present with cholestasis of hepatocellular origin. "Clinical studies on progressive familial intrahepatic cholestasis (PFIC) type 5 caused by mutations in NR1H4 are limited." (PMID 38641832, 2024).
coronary artery disease (6 papers, 2012 to 2024). "Importantly, NR1H4 R436H also associates with lower levels of non-HDL cholesterol and, consistent with this, protects against coronary artery disease." (PMID 30271901, 2018).
liver failure (6 papers, 2016 to 2024). A liver disease characterized by the liver losing or has lost all of its function. "NR1H4-related PFIC is characterized by severe neonatal cholestasis, rapid progression to liver failure, and early death." (PMID 38641832, 2024).
asthma (5 papers, 2020 to 2025). "The farnesoid X receptor (FXR), encoded by the Nr1h4 gene, functions as a bile acid receptor and exerts anti‐inflammatory effects in ovalbumin‐induced rat asthma models." (PMID 41310922, 2025).
bladder cancer (5 papers, 2022 to 2025). "The relationship between the overall disease-free survival and the expression of NR1H4 (FXR) in bladder cancer tissue were analyzed by gene expression profiling interactive analysis (GEPIA)." (PMID 35563650, 2022).
clear cell renal carcinoma (5 papers, 2022 to 2025). A malignant epithelial neoplasm of the kidney characterized by the presence of lipid-containing clear cells within a vascular network. "Genetic alterations and DNA methylation of NR1H4 are strongly associated with patient prognosis in clear cell renal cell carcinoma." (PMID 40656893, 2025). "Nuclear receptor subfamily 1 group H member 4 (NR1H4) have been reported in various cancer types, however, little is known about the clinical values and biological function in clear cell Renal cell carcinoma (ccRCC)." (PMID 36123627, 2022). "In clear cell renal cell carcinoma (CCRCC), high NR1H4 expression facilitates early diagnosis, while its knockdown significantly inhibits cancer cell proliferation, migration, and invasion." (PMID 40656893, 2025).
osteosarcoma (4 papers, 2019 to 2024). A usually aggressive malignant bone-forming mesenchymal neoplasm, predominantly affecting adolescents and young adults. "NR1H4 upregulates the microRNA-23b-3p to regulate the proliferation and apoptosis of osteosarcoma cells." (PMID 36123627, 2022).
biliary atresia (2 papers, 2022). A rare, biliary tract disease characterized by progressive obliterative cholangiopathy of the intra- and extrahepatic bile ducts, occurring in the embryonic/ perinatal period, leading to severe and persistent neonatal jaundice and acholic stool. "Bioinformatics analysis showed that the expression of PPARα, CYP7A1 and NR1H4 (FXR) in the biliary atresia group was significantly lower than in the control group." (PMID 36090996, 2022). "The downregulation of PPARα and NR1H4 (FXR) signaling pathway may be closely related to biliary atresia." (PMID 36090996, 2022).
bladder (2 papers, 2021 to 2025). "NR1H4, also known as Farnesoid X Receptor (FXR), acts as a nuclear receptor that is predominantly expressed in the liver and intestines and can be activated by binding to bile acids (BAs), and altering its expression can influence bladder carcinogenesis." (PMID 40708946, 2025).
squamous cell carcinoma (2 papers, 2021 to 2025). A carcinoma arising from squamous epithelial cells. "Subgroup analysis revealed a similar positive correlation between the gene expression of NR1H4 and TNFRSF14 either in 510 adenocarcinoma or in 484 squamous cell carcinoma samples." (PMID 40985894, 2025).
clear cell carcinoma (1 paper, 2025). "Owing to the rarity of clear cell carcinoma and the limited availability of clinical cases, the roles of NR1H4 and IL4R in OCCC and their associations with immune cell infiltration require further validation through prospective studies with larger sample sizes." (PMID 40656893, 2025).